IGF1 (insulin like growth factor 1)
Diseases named in the same sentence as IGF1 in open-access papers (continued):
Sharing a sentence is not in itself a finding about the gene and the disease.
gastric cancer (continued). "Since our data indicated that benefit of inhibiting IGF1/IGF1R pathway might be limited to MP subtype gastric cancer, possible reasons for current failure might be due to the lack of use of patient enrichment by biomarkers in the trials." (PMID 29725014, 2018). "When MP signature-based BCCP model was applied to gene expression data from these cell lines, Hs746T and SNU1 were predicted as MP subtype while MKN45 and SNU16 were predicted as EP subtype, further supporting molecular correlation between IGF1 expression and MP subtype in gastric cancer cells." (PMID 29725014, 2018). "The role of IGF-1 in protection against anoikis is of particular interest because circulating IGFs could promote survival of detached gastric cancer cells present in serum or ascitic fluid and hence increase their metastatic potential." (PMID 27437872, 2016). "IGF-1 stimulated Akt phosphorylation in all eight gastric cancer cell lines." (PMID 27437872, 2016). "Experimental studies suggest IGF-1 may play a role in the development of gastric cancer." (PMID 37455285, 2023). "In this study, we found that IGF1/IGF1R signaling is highly activated in GC, and inhibition of IGF1R potently suppresses the proliferation of gastric cancer cells." (PMID 36774408, 2023). "Finally, based on the KEGG analysis of Yi-qi-hua-yu-jie-du decoction in gastric cancer treatment and combined with the using of IGF-1 and si-Nrf2, we found that YQHY prevented the activation of the PI3K/Akt/Nrf2 pathway thus to restrain the drug resistance of BGC823/5–Fu-CSCs." (PMID 35941687, 2022). "Here, we report that gastric cancers with a mesenchymal phenotype are associated with poor prognosis, markedly low somatic mutation rates and microsatellite instability (MSI), resistance to standard chemotherapy, and sensitive to inhibition of IGF1/IGF1R pathway." (PMID 29725014, 2018). "In this study, serum levels of IGF signaling pathway-related proteins known as IGF-1, IGFBP-4, IGFBP-5, and PAPP-A were compared between gastric cancer patients and healthy controls." (PMID 41303367, 2025). "This study investigated the biomarker potential of IGF-1, IGFBP-4, IGFBP-5, and PAPP-A in gastric cancer." (PMID 41303367, 2025). "In this study, IGF-1, IGFBP-4, IGFBP-5, and PAPP-A levels were examined in serum samples obtained from gastric cancer patients and healthy individuals." (PMID 41303367, 2025). "IGF-1, which belongs to IGF system, was reported to induce the EMT phenotype and promote cancer proliferation in breast, lung, and gastric Cancers." (PMID 38351014, 2024). "IGF‐1, an AKT agonist, and LY294002, an inhibitor, reversed the effects of KIRREL silencing and overexpression on the PI3K/AKT/mTOR pathway and on gastric cancer cell proliferation and angiogenesis." (PMID 37909722, 2024). "IGF1, upstream growth factor of PI3K-AKT pathway that was recently found to be related with the mesenchymal phenotype of gastric cancer." (PMID 36450891, 2023). "Ginkgo acid (GA), a natural component of ginkgo, nuts, and seed coat, inhibits the migration, proliferation, and EMT of gastric cancer cells by inhibiting SUMO1-mediated SUMOylation of IGF-1 and reducing the expression level of SNA12 and its binding to IGF-1." (PMID 37777749, 2023). "The connection between IGF-1 and ZEB2 was shown in gastric cancer cells, where IGF-1 induced EMT by activation of the PI3K/Akt-GSK-3β-ZEB2 signaling pathway." (PMID 36361979, 2022). "Increased expression of SOX12 was related to gastric cancer cell migration, invasion, and metastasis via transcriptionally targeting matrix metallopeptidase 7 (MMP7) and insulin-like growth factor 1 (IGF1)." (PMID 34745940, 2021). "It was reported that dopamine acting through DRD2, down regulated insulin-like growth factor-1 (IGF-1) and AKT phosphorylation, thereby inhibited gastric cancer proliferation." (PMID 33937078, 2021).
gastric cancer (continued). "Recently, a Japanese study investigated the relationship between insulin‐like growth factor‐1 (IGF‐1) gene rs2195239 polymorphism and gastric cancer (GC) risk and found rs2195239 polymorphism did not relate with the risk of GC." (PMID 32147868, 2020). "Since analysis of genomic data from multiple cohorts suggested activation of the IGF1 pathway in MP subtype, we assessed activation status of the IGF1 receptor (IGF1R) in gastric cancer tissues with western blot experiments." (PMID 29725014, 2018). "Here, we review the tumor-specific molecular signatures of IGF-1-mediated EMT in breast, lung, and gastric cancers." (PMID 30111747, 2018). "Here, we review the state-of-the-art knowledge about the IGF-1-mediated EMT activation with particular focus on the tumor-specific molecular signatures in breast, lung and gastric cancers." (PMID 30111747, 2018). "Another study in Korea examined the change in serum IGF1 and IGF2 levels in 20 stomach cancer cases after surgery using blood samples obtained within 10 days before and once after surgery." (PMID 27144430, 2016). "The serum IGF-1 levels in all gastric cancer patients, regardless of histological differences, were significantly decreased compared to the healthy group (p < 0.05)." (PMID 41303367, 2025). "In conclusion, this study suggests that IGF pathway components, particularly IGF-1, IGFBP-4, and IGFBP-5, might be promising biomarker candidates for gastric cancer." (PMID 41303367, 2025). "Furthermore, STAT3 signaling was reported to be involved in IGF1/IGF1R‐mediated cell growth and metastasis in gastric cancer." (PMID 32851683, 2020). "IGF1/IGF1R/STAT3 signaling promoted IFITM2 expression and gastric cancer growth and metastasis." (PMID 32851683, 2020). "Thus the IGF signal transduction pathway is active and IGF-1 activates both the PI3-kinase/Akt and Ras/Raf/MAP-kinase pathways in gastric cancer cells." (PMID 27437872, 2016). "Previously, EBERs were reported to induce IGF-1 in the EBV-positive C666-1 NPC cell line and in EBER-transfected NPC-derived EBV-negative CNE1 and HONE1 cell lines, as well as in EBER-transfected gastric carcinoma NU-GC-3 cells." (PMID 23292678, 2013). "Moreover, ROC analysis showed that IGF-1, IGFBP-4, and IGFBP-5 could effectively distinguish gastric cancer from healthy controls with high sensitivity and specificity." (PMID 41303367, 2025). "In addition, SOX12 can promote gastric cancer metastasis by up‐regulating MMP7 and IGF1." (PMID 41425852, 2025). "Insulin, insulin-like growth factor 1(IGF1) and insulin-like growth factor 2(IGF2) were the most studied insulin-like peptides (ILPs) regarded as key regulators of energy metabolism and growth, especially IGF1 receptor and IGF2 receptor were expressed in gastric carcinoma cells." (PMID 30299268, 2018). "In gastric cancer cells it has been shown that IGF1 is able to induce EMT through the up-regulation of ZEB2, in addition, AKT1/ERK inhibitors revert IGF1-induced EMT through up-regulation of miR-200c, suggesting the involvement of an AKT1/ERK-miR-200c-ZEB2 axis in EMT induced by IGF1 stimulation." (PMID 28880250, 2017). "That IGF-1 protects against apoptosis induced by the kinase inhibitor staurosporine emphasizes the potency of IGF-1 as a pro-survival factor and suggests that it may protect gastric cancer cells from therapeutic kinase inhibitors." (PMID 27437872, 2016). "Patients with gastric cancer may show serum IGF-1 levels significantly increased over normal limits." (PMID 25006674, 2014). "Besides TGF-β signaling, the insulin-like growth factor (IGF) signal transduction cascade is crucially involved in EMT in gastric cancer, where MMP11 knockdown was able to diminish IGF1 signaling and concomitantly reduced the invasive potential of gastric cancer cells." (PMID 35269560, 2022).
Cirrhosis (74 papers, 2005 to 2026). A chronic disorder of the liver in which liver tissue becomes scarred and is partially replaced by regenerative nodules and fibrotic tissue resulting in loss of liver function. "Clinically, reduced levels of IGF-1 are frequently associated with advanced stages of liver disease such as cirrhosis and HCC." (PMID 39624154, 2025). "IGF-1 administration in mouse models with methionine-choline-deficient diet-induced nonalcoholic steatohepatitis and dimethylnitrosamine-induced cirrhosis ameliorated hepatic steatosis, inflammation, and fibrosis." (PMID 37554499, 2023). "Low serum IGF-1 levels were significantly and independently associated with decompensation development and poor long-term prognosis in patients with compensated cirrhosis." (PMID 37554499, 2023). "In the univariate analysis, CP score, total bilirubin, albumin, PT, IGF-1, and M2BPGi were significantly associated with decompensation development in patients with compensated cirrhosis." (PMID 37554499, 2023). "Reportedly, circulating IGF-1 levels decrease with disease progression, and the decreased levels are associated with poor short-term prognosis in patients with cirrhosis, especially decompensated cirrhosis." (PMID 37554499, 2023). "In conclusion, low serum IGF-1 levels were associated with decompensation development and poor long-term prognosis in patients with compensated cirrhosis." (PMID 37554499, 2023). "The present study is the first to report the association between serum IGF-1 levels and long-term prognosis in patients with compensated and decompensated cirrhosis, respectively." (PMID 37554499, 2023). "Circulating levels of insulin-like growth factor-1 (IGF-1) are diminished in advanced cirrhosis due to the loss of biosynthetic mass." (PMID 28472963, 2017). "IGF-1 significantly decreased with the progression of cirrhosis and IGF-1 less than 30 ng/ml was associated with a poor prognosis." (PMID 23599716, 2013). "Multivariate analysis identified low serum IGF-1 levels as a significant and independent factor associated with mortality (all patients: hazard ratio [HR], 0.967; p = 0.004; patients with compensated cirrhosis: HR, 0.927; p = 0.002)." (PMID 37554499, 2023). "This reduction in IGF-1 levels is associated with impaired liver function and reflects a state of resistance to GH, often seen in cirrhosis, where the liver’s ability to produce IGF-1 deteriorates." (PMID 40806358, 2025). "For example, reduced hepatic synthesis of insulin-like growth factor-1 (IGF-1) plays a notable role in the progression of cirrhosis by promoting liver steatosis and impairing liver regeneration." (PMID 40806358, 2025). "Experimental rodent models have indicated that augmenting IGF-1 signaling can enhance muscle regeneration and metabolism, suggesting a promising frontier for clinical application in cirrhosis management." (PMID 40806358, 2025). "Lower levels of circulating IGF-1 showed lower survival rates in patients with cirrhosis than those with high plasma IGF-1 levels." (PMID 39781288, 2025). "Whole-genome sequencing revealed heterozygosity for a rare variant of the IGF-1 receptor, a metabolic factor whose role is crucial in the GH/IGF-1 axis to fatty liver and cirrhosis." (PMID 39781288, 2025). "Blood tests showed mildly low levels of insulin like growth factor 1 (IGF1), which was considered to be influenced by cirrhosis." (PMID 39040756, 2024). "IGF‐1, on the other hand, can induce cellular senescence and deactivate hepatic stellate cells, mitigating cirrhosis." (PMID 38887910, 2024). "We divided the patients into the compensated and decompensated cirrhosis groups and compared the cumulative survival rates among the three IGF1 groups in each cirrhosis group." (PMID 37554499, 2023). "Our study revealed that the median IGF-1 levels were 62, 43, and 34 ng/mL for CP class A, B, and C, respectively, and 61 and 46 ng/mL for compensated and decompensated cirrhosis, respectively." (PMID 37554499, 2023).
Cirrhosis (continued). "This study aimed to investigate the usefulness of serum IGF-1 levels for predicting the long-term prognosis of patients with cirrhosis and the difference in the predictive performance of IGF-1 between patients with compensated and decompensated cirrhosis." (PMID 37554499, 2023). "We retrospectively evaluated 148 patients with cirrhosis and divided them into three groups according to baseline IGF-1 levels: low (L)-, intermediate (I)-, and high (H)-IGF-1 groups." (PMID 37554499, 2023). "This study aimed to investigate the usefulness of serum IGF-1 levels for predicting the long-term prognosis and decompensation development in patients with cirrhosis." (PMID 37554499, 2023). "A pilot study of patients with cirrhosis revealed that IGF-1 administration for 4 months increased serum albumin levels and improved energy metabolism, as assessed by resting energy expenditure." (PMID 37554499, 2023). "IGF-1 levels in healthy individuals are influenced by age, sex, and nutritional status, but it has been reported that patients with cirrhosis have decreased IGF-1 and increased GH levels due to positive feedback effects." (PMID 38024081, 2023). "Serum IGF-1 levels in patients with decompensated cirrhosis were significantly lower than in those with compensated cirrhosis (median, 46 ng/mL vs. 61 ng/mL; p < 0.001)." (PMID 37554499, 2023). "The mechanism of low IGF-1 in cirrhosis is thought to be impaired IGF-1 synthesis in the liver, as well as hepatic GH resistance associated with liver dysfunction." (PMID 38024081, 2023). "A previous study revealed significantly lower 2 years survival rates in inpatients with cirrhosis with low plasma IGF-1 levels than those with high plasma IGF-1 levels." (PMID 37554499, 2023). "Recent pre-clinical studies suggest that the anomalies of the GH/IGF1 axis are associated with a higher prevalence of steatosis, with a more rapid progression towards non-alcoholic steatohepatitis (NASH), cirrhosis and end-stage liver disease." (PMID 36557260, 2022). "Although we excluded patients with hepatic cirrhosis from this study, liver-produced IGF-1 can be affected by the conditions of nonalcoholic fatty liver disease." (PMID 36418379, 2022). "Conversely, the cirrhosis group had significantly lower serum IGF-1 levels than the non-cirrhosis group (p < 0.001)." (PMID 36010307, 2022). "Even though GH levels are high in cirrhosis, decreased IGF-1 and IGFBP3 synthesis by the liver induce growth hormone resistance." (PMID 34205986, 2021). "Nevertheless, a reduction in REE after IGF-1 replacement suggested a role of IGF-1, and the GH axis respectively, in reducing the hypermetabolism associated with cirrhosis." (PMID 32731496, 2020). "In murine models of NASH and cirrhosis, administration of IGF-1 consistently improved steatosis, inflammation, and fibrosis with inactivation of HSC." (PMID 30700007, 2019). "In clinicopathological researches, serum IGF-1 level and tissue expression of IGF-1 decrease in liver diseases, including hepatic steatosis, fibrosis, and cirrhosis; whereas systemic IGF-1 administration can ameliorate liver function and fibrosis." (PMID 31171766, 2019). "In cases of HCC, significant reduction of serum IGF1 levels as compared to cirrhosis and healthy controls was observed." (PMID 29702590, 2018). "A prospective study on 114 hepatitis C virus-related cirrhosis patients revealed that insulin-like growth factor 1 (IGF-1) is inversely correlated with the onset of HCC12." (PMID 29872158, 2018). "IGF1 concentration decreased with the severity of cirrhosis (Child–Pugh score), reaching significantly low values in class C." (PMID 29702590, 2018). "A rapid and significant increase in IGF1 concentrations were noted in patients after liver transplantation due to cirrhosis." (PMID 29702590, 2018).
Cirrhosis (continued). "Second, chronic HBV infection associated liver decompensation and cirrhosis can impair insulin-like growth factor 1(IGF-1) produced by liver, which inhibit osteoblast differentiation and proliferation promoted by IGF-1." (PMID 28523056, 2017). "HCC was associated with a significant reduction in serum IGF-1 and IGFBP-3 levels compared to cirrhosis (p = 0.037)." (PMID 29113370, 2017). "Cell necrosis, oxidative damage, and fibrogenesis are involved in cirrhosis development, a condition in which insulin-like growth factor 1 (IGF-1) levels are diminished." (PMID 28472963, 2017). "We thought that cirrhotic livers had the lowest IGF-1 levels caused by IGF-1 was exhausted and simply cannot produce IGF-1 under cirrhosis conditions." (PMID 27279075, 2016). "The majority of GH dependent serum IGF1 is hepatic derived and patients with hepatic cirrhosis exhibit decreased serum IGF1 with concomitant elevated GH indicative of hGH resistance." (PMID 27102295, 2016). "The decrease of circulating IGF-1 in patients with cirrhosis or HCC has been attributed to a result of liver damage because hepatocytes are the main contributors of IGF-1." (PMID 24595361, 2014). "Liver diseases such as cirrhosis are characterized by a deranged GH-IGF-1 system, with increased levels of GH and reduction in IGF-1 production." (PMID 24804205, 2014). "Our findings showed that IGF-1 can be used as an index for evaluating the severity of cirrhosis; also it can be used for determining the severity of the disease, when liver biopsy is not possible." (PMID 23599716, 2013). "The results of our study suggest that IGF-1 can be an index of severity of cirrhosis and also a marker of liver function; thus can be used for determining severity of the disease in patients in which liver biopsy is not possible." (PMID 23599716, 2013). "This decrease in IGF-1 is because of two factors; firstly, the decrease in growth hormone receptors in patients with cirrhosis and secondly progressive reduction in production of IGF-1 that is due to a decrease in hepatocytes." (PMID 23599716, 2013). "In humans, IGF-1 levels decline with cirrhosis progression and correlate with increased frailty." (PMID 41458554, 2025). "Furthermore, a small randomized trial in hypogonadal men with cirrhosis found that testosterone therapy, which can enhance IGF-1, significantly increased lean mass and improved BMD after 12 months." (PMID 41458554, 2025). "Furthermore, we evaluated the usefulness of serum IGF-1 levels for predicting decompensation development in patients with compensated cirrhosis." (PMID 37554499, 2023). "Insulin-like growth factor 1 (IGF-1), which is primarily produced in hepatocytes and is associated with liver functional reserve, plays a crucial role in the pathological condition of cirrhosis." (PMID 37554499, 2023). "However, the liver’s ability to synthesize GH receptors is declined and GH resistance is observed when liver function is impaired in cirrhosis, resulting in increased serum GH levels and decreased IGF-1 levels." (PMID 37881635, 2023). "Based on in vitro experiments, IGF-1 might serve as a potential therapeutic target for cirrhosis and intestinal barrier dysfunction via its inactivation of the TLR4/MyD88/NF-κB pathway." (PMID 36330225, 2022). "IGF-1 (growth factor-1) has been widely reported that its expression decreased sharply in patients with chronic liver disease such as steatosis, nonalcoholic steatohepatitis, chronic hepatitis C, cirrhosis, and HCC." (PMID 35196258, 2022). "Serum IGF-1 levels are decreased in cirrhosis as the synthetic capacity of the liver is diminished." (PMID 34205986, 2021). "Similarly, in a rat model of cirrhosis, treatment with IGF-1 was demonstrated to increase mitochondrial membrane potential and ATP synthase activity and to reduce intramitochondrial free radical production, caspase activation, and apoptosis." (PMID 32701508, 2020).